IL10 (interleukin 10)
Diseases named in the same sentence as IL10 in open-access papers (continued):
Sharing a sentence is not in itself a finding about the gene and the disease.
Sepsis (continued). "Whether IL-10 is produced by MDSCs directly, or if it acts indirectly on MDSCs or other cells involved in the sepsis response remains to be determined." (PMID 37681975, 2023). "It was found that supplementation with omega-9, or oleic acid, is crucial in the metabolic dysfunction that occurs during sepsis because it increases the levels of the anti-inflammatory cytokine IL-10, lowers levels of the pro-inflammatory cytokines TNF- and IL-1, and inhibits neutrophil migration." (PMID 37764396, 2023). "The up-regulating of the production of IL-10 has beneficial effects in sepsis mouse models." (PMID 37561521, 2023). "Furthermore, IL-10 is expressed by many innate and adaptive immune response cells, thus it plays an important role in the early diagnosis of sepsis in neonates." (PMID 38027268, 2023). "Chorioamnionitis predisposes infants to PDA.Late-onset sepsis is associated with a higher rate of unsuccessful DA closure with treatment.Large PDA is associated with increased pro-inflammatory (IL-1β, IL-8) and anti-inflammatory (IL-1Ra, IL-10) cytokines." (PMID 36994431, 2023). "MDSCs sustain the protracted immune suppression phase of sepsis, as they produce anti-inflammatory mediators, such as TGFβ, IL-1, IL-10, and arginase, anti-inflammatory cytokines limit cell proliferation and effector functions, and expand and activate Treg cells." (PMID 39665047, 2023). "Secondly, the potential therapeutic value of Interleukin-10 (IL-10) proposed in this study for IE and sepsis, as well as the mode of action of matrine, although theoretically grounded, indeed demands further empirical research for validation and deeper exploration." (PMID 38332910, 2023). "Providing clinical relevance, significantly higher concentrations of IL-33 and IL-10, as well as increased frequencies of Tregs, have been detected in the circulation of sepsis survivors sampled 5-10 months post-diagnosis when compared to age and sex-matched controls." (PMID 37662933, 2023). "During the early phase of sepsis, restauration of immunosuppressive cytokines, such as IL-10, may be in line with organ function recovery and improved survival." (PMID 37575989, 2023). "Finally, we show that the G-MDSC subset predominates systemically following immunization, and this subset and anti-inflammatory IL-10 are required for MDSC-mediated protection against lethal sepsis." (PMID 37681975, 2023). "The results indicate that, based on the IE dataset GSE29161 as well as the sepsis datasets GSE57065, GSE69063, GSE95233, GSE131761 and GSE185263, IL10 shows a significant correlation with diagnostic genes." (PMID 38332910, 2023). "When the efferocytically-licensed monocytes were subsequently challenged with a cocktail of LPS, IFN-γ, and IL-2 to simulate sepsis, we saw IL-10 increase in all samples, but only monocytes efferocytically-licensed with viable MSC significantly increased output of kynurenine." (PMID 37592321, 2023). "We determined whether the increase in S100A9 phosphorylation following Hotairm1 knockdown decreased IL-10 levels in late sepsis Gr1+CD11b+ cells." (PMID 39665047, 2023). "Interleukins have been of recent interest as potential treatment in sepsis due to their contribution to thrombosis and their potential therapeutic effect in animal models, including pro-inflammatory IL-6 and anti-inflammatory IL-10." (PMID 36261775, 2022). "More importantly, “IL-6 IL-10 ratio” could easily reflect the extent of pro-inflammatory and anti-inflammatory status during sepsis, which is crucial in sepsis progression." (PMID 36544765, 2022). "However, “IL-6 IL-10 ratio” was relatively lower in G- sepsis patients with bloodstream infection and ARDS." (PMID 36544765, 2022). "Although the levels of serum cytokines (tumor necrosis factor [TNF], interleukin [IL]-6, interferon [IFN]-γ, and IL-10) were drastically increased in burn-injured mice under sepsis, pioglitazone reduced the peak level of TNF and continuous production of IL-10 after infection." (PMID 36361535, 2022).
Sepsis (continued). "However, for patients with progressively deteriorating organ function [new or progressive multiple organ dysfunction syndrome (NPMODS)], differences in IL-6 and IL-10 levels were less significant between G+ and G- sepsis." (PMID 36544765, 2022). "IL-10 is a pleiotropic cytokine with an immunomodulatory effect, which is produced by a variety of different cell types (macrophages, lymphocytes, fibroblasts) during influenza and sepsis and acute organ injuries." (PMID 35740951, 2022). "In addition, we also wanted to develop an engineered macrophage in this study and provide a basis for the next step of exosome‐based IL10 delivery in sepsis treatment." (PMID 35015384, 2022). "Results of this research showed that TNF-α and neutrophils decreased gradually in the CLP and LBP groups in contrast to a persistent increase of IL-10, suggesting that the body was dominated gradually by anti-inflammatory reactions and sepsis entered the status of immunosuppression." (PMID 36248408, 2022). "Hierarchical clustering analysis showed that resistin and inflammatory cytokines formed a network that includes interleukin (IL)-6, IL-8, IL-10 and monocyte chemotactic protein 1 (MCP-1) in the acute phase of sepsis and burns and that this network is associated with severity and prognosis." (PMID 35784283, 2022). "It will also find out what value an optimal infection level is for sepsis patients and evaluate whether IL-10, IL-17, and PCT have a net clinical benefit in patients with sepsis infection." (PMID 35937269, 2022). "Whether extracellular vesicle‐encapsulated IL‐10 isolated from IL10‐eM supernatant could serve as nanotherapeutics against sepsis is what we are going to do in the follow‐up study." (PMID 35015384, 2022). "Additionally, sepsis induced higher expression of IL-6 and IL-10 by liver macrophages, with in vivo blocking of CD1d leading to reduction of IL-6 and augmentation of IL-10 systemic levels, further improving survival rates." (PMID 35163561, 2022). "Correlation analysis showed that peripheral mtDNA levels may be related to plasma IL‐10, indicating that mtDNA may mediate immunosuppression in sepsis." (PMID 36106559, 2022). "This study is only a in vitro cellular experiment and further animal model evidence is needed to test whether the supernatant of IL10‐eM can protect the vascular injury and prevent leakage in sepsis." (PMID 35015384, 2022). "In contrast, the concentration of IL-10 in sepsis patients significantly increased even beyond values seen in samples from healthy subjects following stimulation with the TLR4 ligand (p = 0.0036), but not significantly following stimulation with TLR2 or 7/8 ligands." (PMID 35981050, 2022). "Numerous studies of sepsis in adults have shown increases in percent Tregs and Treg activity (as measured through cytokine expression of IL-10 and TGF-β and as expression of CTLA-4 and FOXP3 on the cell surface) and implicate Tregs in adaptive immune suppression." (PMID 35958579, 2022). "Study has shown that IL-10 monitoring from day 1 to day 3 after the onset of sepsis may help predict the prognosis of septic patients." (PMID 36209190, 2022). "Subgroup analysis revealed that for sepsis patients characterized by progressive organ dysfunction, levels of IL-6 and IL-10 were less helpful in identifying bacterial Gram types while more strongly correlated with NPMODS but independent of baseline organ dysfunction." (PMID 36544765, 2022). "We detected the expression levels of TNF-α, IL-1β, IL-6, and IL-10 in sera and BALF of septic mice using ELISA, and the results indicated that Fer-1 reduced the upregulation of the expression levels of inflammatory factors caused by sepsis in mice (P < 0.05)." (PMID 35910848, 2022). "Compared with G+ sepsis, IL-6 and IL-10 were significantly elevated in G- sepsis (p < 0.05)." (PMID 36544765, 2022). "In addition to their cytolytic capacity, NK cells conventionally produce IFN-γ, but can produce IL-10 in response to IL-15 during sepsis." (PMID 35878936, 2022).
Sepsis (continued). "HgSMs are characterized by the simultaneous increased release of inflammatory and anti-inflammatory mediators, such as TNF-α and IL-10, indicative of a condition that has been termed as immunoparalysis, as it occurs in patients affected by sepsis and septic shock." (PMID 35247131, 2022). "Multivariate logistic regression linked IL-10, IL-17, and PCT to sepsis risk." (PMID 35937269, 2022). "Neutrophils are significant contributors of IL-10 at the site of infection during sepsis." (PMID 36139764, 2022). "Despite associations of lower human leukocyte antigen expression and increased interleukin-10 (IL-10) levels with ICU-acquired infection, identifying which patients are at a higher risk of sepsis-associated ICU-acquired infection remains clinically challenging." (PMID 35967847, 2022). "The IL-10, IL-17, and PCT tests all have a high diagnostic value for patients with sepsis, and the combination of the three tests outperforms the individual tests in terms of diagnostic performance, while the combined tests have a higher overall clinical benefit rate." (PMID 35937269, 2022). "IL-10 was also related with greater inflammatory markers in the sepsis group." (PMID 35937269, 2022). "Also, significantly lower levels of IL-4 (p<0.0001), IL-10 (p<0.0001), and IL-13 (p<0.05) were measured/detected in children with sepsis compared to children with clinical malaria." (PMID 35811678, 2022). "However, treatment with ICOS-Fc significantly decreased IL-1β and TNF-α in WT mice and IL-1β, IL-6 and IL-10 in ICOS-/- mice indicating that ICOS-Fc substantially downmodulates the cytokine storm in sepsis." (PMID 36119089, 2022). "IL-10 is an anti-inflammatory cytokine that plays a key role in the pathogenesis of sepsis." (PMID 35937269, 2022). "Meanwhile, Breg cells can also negatively regulate the immune responses, mainly by producing anti-inflammatory factors such as IL-10 and IL-35 to induce endotoxin tolerance or immunosuppression, inhibit innate immune responses and promote Treg responses in sepsis." (PMID 36425582, 2022). "Interestingly, in an experimental abdominal murine sepsis model, neutrophil IL-10 production was induced by IFN-γ from CD4+ T cells, thereby dampening local inflammation." (PMID 35732880, 2022). "In addition to this response, immunosuppressive cytokine IL-10 is enormously produced by the neutrophils during sepsis to promote infection." (PMID 35923679, 2022). "At the Fluids time-point, circulating levels of pro-inflammatory cytokines (TNF-α and IL-6) had increased similarly in the two treatment groups in response to sepsis; Anti-inflammatory IL-10 levels were increased in the Ang II group at VP1 compared to baseline." (PMID 36117167, 2022). "Among all Th1/Th2 cytokines, IL-6 and IL-10 were particularly elevated in G- sepsis patients." (PMID 36544765, 2022). "Correlation analysis showed that the level of IL-10 in serum was positively correlated with the proportion of MDSCs, because IL-10 drives the signaling pathway that generates MDSCs and enhances immunosuppression during late sepsis, and blocking IL-10 prevents MDSC expansion during late sepsis." (PMID 36263056, 2022). "In addition, the immunosuppressive effect of sepsis is augmented by release of IL-4 and IL-10, both of which were shown to reduce expression of pro-inflammatory cytokines." (PMID 35879778, 2022). "Sepsis-related anti-inflammatory cytokines mainly include IL-4, IL-10, and IL-37." (PMID 36209190, 2022). "Modulation of IL-10 expression by MSCs has previously been reported in in vivo models of inflammatory and neuropathic pain, but also in many other models of inflammation, e.g. sepsis, osteoarthritis or traumatic brain injury." (PMID 34716556, 2022). "Finally, high levels of MIF and IL-10 were both found to have bad prognostic value for the fatal outcome of sepsis patients, where high levels of IL-10 were found to have the highest prognostic value." (PMID 35464430, 2022).
Sepsis (continued). "Therefore, MZ B cells can play a dual regulatory role in the inflammatory response to sepsis by producing pro-inflammatory factors such as IL-6 and anti-inflammatory factors such as IL-10." (PMID 36425582, 2022). "However, plasma levels of IL-10, IL-6, and IL-8 were significantly increased in sepsis compared to HCs and w/o sepsis patients." (PMID 35720398, 2022). "This suggested that DEX could reduce the levels of TNF-α, IL-1β, and IL-10 after sepsis induction at the early stage." (PMID 33981237, 2021). "IL-10 is considered anti-inflammatory, but has been noted to be higher in sepsis patients, proposed the increase might be an attempt to moderate the immune response." (PMID 34000622, 2021). "IL-10 has been associated with high mortality rate in ARDS and we have earlier reported its expression along with pro-inflammatory cytokines in a model of sepsis." (PMID 33632209, 2021). "The upregulation of IL-10 in sepsis is concordant with the lower methylation levels we found in its promoter and may contribute to the immunosuppressive response in neonatal sepsis." (PMID 33659006, 2021). "Sepsis elevated IL-10 and TNF-α among WT mice, but this effect was lost among PD1−/− murine lungs." (PMID 33746973, 2021). "In addition, Il-10-deficient mice are extremely sensitive to low doses of LPS (5 μg/mouse) and have increased mortality during endotoxemia, a mouse model for sepsis, that is mitigated by Il-10 infusion." (PMID 34502552, 2021). "Compared with APAP-treated PD-1–/– mice, APAP-treated WT mice had a higher fold change of C-reactive protein (CRP) and lactate levels and a cytokine profile that favored a proinflammatory imbalance, as indicated by increased sepsis severity markers such as IL-6 and a higher IL-6/IL-10 ratio." (PMID 33320839, 2021). "In light of published evidence associating IFNγ and IL10 with the severity of parasitic infection and tuberculosis, we investigated whether IFNγ/IL10 reflects the pathogen burden of immune cells when challenged with typical pathogens found in sepsis." (PMID 33767693, 2021). "Other studies have reported the presence of an immunosuppressive neutrophil subset during sepsis, as characterized by the increased production of large amounts of the immunosuppressive cytokine IL-10 and further suppression of T cell proliferation and function." (PMID 33532141, 2021). "First, the clinical findings could not provide direct evidence demonstrating the participation of lactate-induced H3K18la in the regulation of IL-10 in sepsis." (PMID 35069560, 2021). "Combined with the significant relationship with IL-10, H3K18la might not only differentiate patients with sepsis but also indicate prognosis." (PMID 35069560, 2021). "Furthermore, in a systematic sepsis model in mice, lipoplex-delivered IL-10 significantly prevented lung and other organ injury." (PMID 35111077, 2021). "Several studies have shown that IL-10 is detected in the serum of patients with sepsis." (PMID 33917002, 2021). "As sepsis-induced disruption of tissue homeostasis leads to aberrant regulation of both anti- and pro-inflammatory cytokines (CKs), we sought to determine the expression of IL-1β, IL-6, IL-10, TGF-β1, and TNFα, the main drivers of tissue inflammation." (PMID 33803290, 2021). "Salivary IL-10 could serve as potential noninvasive biomarker for the diagnosis of late-onset sepsis in full-term neonates." (PMID 34676267, 2021). "In addition to the IL-10-producing subset, a new subset of B cells, which was coined innate response activator B cells, has been described in a murine sepsis model." (PMID 33021569, 2021). "In addition to CRP and PCT, the concentrations of the circulating anti-inflammatory cytokines IL-Ra and IL-10 were found to be significant in discriminating between sepsis and SIRS55–57." (PMID 34675320, 2021). "Finally, the importance of the IL-6/IL-10 balance was stressed in predicting the sepsis outcome and mortality." (PMID 33500240, 2021).
Sepsis (continued). "In addition, the concentration of plasma IL-10 correlated with the concentration of IL-6, suggesting that IL-10 is produced to regulate the inflammatory response typically mediated by IL-6 in sepsis." (PMID 35053151, 2021). "Additionally, in the CLP sepsis mouse model, EVs derived from the serum of LPS-treated mice have an attenuative effect on inflammation, reflected by reduced serum levels of IL-10 and TNF in CLP mice 8 h after EV injection." (PMID 34451925, 2021). "At the late stage of sepsis, the anti-inflammatory state may appear, showing a high expression of IL-10, which may result in a further impaired immune response with an increased risk of nosocomial infections." (PMID 34204220, 2021). "More recently, however, it has been shown that in sepsis, IL-10 may stimulate and oppose IFN-γ and TNF-α production in mononuclear cells and T cells, respectively." (PMID 34938289, 2021). "We detected a prominent effect of AE administration downregulating BALF levels of CXCL-1 (P < 0.05), CXCL-8 (P < 0.01), IL-6 (P < 0.05), IL-10 (P < 0.01), and TNF-α (P < 0.001) and upregulating BALF levels of IL-10 (P < 0.05) and IL-1RN (P < 0.05) during sepsis." (PMID 34493741, 2021). "In a study that collected serial samples from patients meeting sepsis-3 criteria until discharge, differences in cytokine measurements on Day 1 of sepsis were seen, where IL-1β, IL-10, IL-6, and IL-8 levels were among six cytokines found to be significantly elevated compared to controls." (PMID 33820537, 2021). "IL-10 is a well-known anti-inflammatory factor that induces an immune repressor pathway in sepsis." (PMID 33819192, 2021). "The results of this study showed that gut-origin sepsis was associated with increased expression of the proinflammatory cytokines (TNF-α, IL-1β, IL-6, and HMGB1) and decreased expression of anti-inflammatory cytokine IL-10." (PMID 34790828, 2021). "The others supplementations display extremely low IL‐10 level even 2 h after sepsis induction." (PMID 34288548, 2021). "H3K18la-mediated anti-inflammatory effects, such as IL-10 overexpression, may play an important role in the anti-inflammatory function of macrophages as well as Arg1 expression in sepsis." (PMID 35069560, 2021). "Likewise, in experimental sepsis in rats HBO2 treatment has shown to stimulate immune‐modulatory activities including IL‐10 modulation resulting in improved survival, but timing and dosage are essential factors for the overall outcome." (PMID 33719215, 2021). "Consistent with other studies, critical-deceased patients elevated the levels of IL-10, which might be responsible for the secondary infections, sepsis, and T cell exhaustion." (PMID 34712742, 2021). "Sepsis-induced inflammation wasassessed by measuring interleukin-6 (IL-6), IL-10 and HMGB1 levels." (PMID 33605309, 2021). "TNFα, IL-6, IFNγ, IL-1β and IL-10 were measured in brain of mice 6 h after induction of sepsis." (PMID 33608025, 2021). "Accordingly, salivary IL-10 could serve as a potential noninvasive biomarker for the diagnosis of late-onset sepsis in full-term neonates." (PMID 34676267, 2021). "Indeed, IL-1b and IL-10 levels were higher in patients who deteriorated compared to those who improved only in the group of patients with sepsis with sufficient predictive value (AUROCs 0.71 and 0.72, respectively)." (PMID 33917002, 2021). "This study found that GDF15 is positively correlated with IL-6 and IL-10, which may be due to the rapid increase of cytokines after the cytokine storm in sepsis." (PMID 34566964, 2021). "Targeting IL-17A enhanced IL-10 production in peripheral blood mononuclear cells following sepsis." (PMID 32849528, 2020). "Also, the impaired phagocytic activity of AMs during late stages in response to the released IL-10 during abdominal sepsis further enhances the incidence and the severity of sepsis-induced ALI." (PMID 32849610, 2020).